STAT1 (signal transducer and activator of transcription 1)
Diseases named in the same sentence as STAT1 in open-access papers (continued):
Sharing a sentence is not in itself a finding about the gene and the disease.
tumor (continued). "Tumor-associated CD11b+ cells were then transfected with lentivirus carrying either pLKO shRNA control or STAT1 targeting shRNAs (Methods section)." (PMID 37055410, 2023). "Expression of STAT1 by M1 GAMs promotes their antitumoral function due to the tumor suppressor activities associated with STAT1 expression." (PMID 37304294, 2023). "T cells from tumor-bearing Stat1-deficient mice display attenuated IFNγ production and upregulation of immunosuppressive cytokines." (PMID 37444444, 2023). "In tumor-associated macrophages (TAMs), STAT1 regulates the expression of arginase and NO, which in turn suppresses T cell-mediated immune responses and induces T cell apoptosis." (PMID 36911202, 2023). "IL-12 induces a high intensity of tumor-specific CTL activity in STAT1-deficient mice, increases the CD8+ T-cell density, and induces a T-cell-dependent tumor regression." (PMID 36911202, 2023). "It has been demonstrated that STAT1 deficiency promotes rapid and extensive intestinal damage, leading to increased proliferation in the early stages of induced tumor formation and reduced apoptosis in advanced tumors." (PMID 36982677, 2023). "Although our study demonstrated a relatively weak association between STAT1 and ICB responses, STAT1 expression in the HCC tumor microenvironment remains a potential predictive marker and warrants more in-depth evaluation." (PMID 37342338, 2023). "Stat1-deficient mice orthotopically injected with LY2 HNSCC cells are highly susceptible to tumor growth and metastasis and are associated with an exhausted T cell phenotype with enhanced PD1 expression." (PMID 37444444, 2023). "Next, we validated STAT1’s role in regulating tumor-associated PD-L1+ myeloid cells by knocking down STAT1 in tumor-associated CD11b+ cells." (PMID 37055410, 2023). "STAT1 is considered as a tumor suppressor, linked with the M1 phenotype, whereas STAT3 is thought as a tumor promoter." (PMID 38098217, 2023). "IRF1 is a target gene downstream of the IFN-γ/JAK/STAT1 pathway, and its deficiency can reduce tumor progression." (PMID 37185662, 2023). "Stat1-deficient mice displayed increased oral lesion incidence and multiplicity during tumour carcinogenesis in vivo." (PMID 35595823, 2022). "This was associated with an exhausted T cell phenotype with increased programmed cell death protein 1 (PD-1) expression, and increased accumulation of immunosuppressive myeloid-derived suppressor cell (MDSC) populations in the tumours of Stat1-deficient mice." (PMID 35595823, 2022). "Depletion of autophagy elongation proteins induces ISG15 expression through STAT1 activation, resulting in the acquisition of tumor-associated phenotypes such as cell proliferation, migration, and invasion." (PMID 36319753, 2022). "This contrasts with our previous findings where these populations significantly accumulate in Stat1-deficient mice bearing Stat1 competent aggressive HSNCC tumours." (PMID 35595823, 2022). "STAT1 acts as a tumour suppressor in a range of cancer types and is associated with the expression of Bcl-xL and cyclin D1." (PMID 35781872, 2022). "Specifically, Vit-C stimulates TET2, which in turn activates IRF1, which eventually binds to STAT1, to enhance the expression of PD-L, making tumor cells more susceptible to immunotherapy." (PMID 35745630, 2022). "STAT1 has a dual function in the TME of radioresistant cells by either protecting radiation-induced damage or mediating tumor cell apoptosis, which associates STAT1 with radio-resistance." (PMID 36032151, 2022). "The JAK/STAT pathway is often associated with pro-tumorigenic activity; however, STAT1, as a tumor suppressor, modifies the immune profile of tumor cells and their response to therapy." (PMID 35884974, 2022). "We also used the 4-nitroquinoline-1-oxide (4NQO) carcinogen-induced HNSCC model in STAT1-competent and STAT1-deficient mice to determine the effect of STAT1 on tumour development and immune responses to HNSCC in vivo." (PMID 35595823, 2022).
tumor (continued). "Tumor growth, as well as tumor‐associated macrophage polarization, depends on the status of the STAT1:STAT3 ratio." (PMID 34689394, 2022). "High STAT1 expression was significantly associated with clinical stage, age, histological type, residual tumor, histological grade, and median survival age of UCEC." (PMID 35244291, 2022). "Given the decreased anti-tumour activity in the STAT1-deficient tumour microenvironment, we analysed T-cell populations of the oral draining lymph nodes and spleens of experimental mice." (PMID 35595823, 2022). "We used an orthotopic model of metastatic HNSCC cells injected into Stat1-deficient (Stat1−/−) or Stat1-sufficient (Stat1+/+) mice to show that mice deficient in Stat1 are highly susceptible to tumour growth and metastasis." (PMID 35595823, 2022). "Collectively, these data suggest that Siglec-15 promotes tumor progression and the activation of STAT1/STAT3 signaling pathway, which is associated with tumor immunity." (PMID 35769818, 2022). "The results showed that the expression levels of STAT1/3/4/5B were significantly associated with the tumor stage of patients with CRC." (PMID 36061181, 2022). "Our current results show that global STAT1 deficiency in a carcinogen-induced model of HNSCC leads to decreased PD-1/PD-L1 expression in the tumour microenvironment and by immune cells." (PMID 35595823, 2022). "Immunosuppressive markers PD-1 in CD8+ T cells and PD-L1 in monocytic MDSCs and macrophages were reduced in oral tumours and draining lymph nodes of tumour-bearing Stat1-deficient mice." (PMID 35595823, 2022). "Specifically, we measured IFN-γ, GranzymeB, and CXCL9, markers known to be regulated by STAT1 and are associated with T cell anti-tumour activity, effector responses and chemotaxis of anti-tumour effector T cells." (PMID 35595823, 2022). "We next analyzed tumor prognosis and identified STAT1 to be independently associated with poor prognosis of GC with a hazard ratio (HR) (95% confidence interval [CI]) of 2.34 (1.04–5.30) after adjusting for age, sex, TNM stage, and Lauren type." (PMID 35456965, 2022). "Taken together, our results indicate that despite the pro-tumorigenic properties of STAT1 in HNSCC tumour cells, global STAT1 deficiency results in higher tumour burdens in the carcinogen-induced model of HNSCC carcinogenesis." (PMID 35595823, 2022). "This strongly supports the theory that BGS treatment mediates CD8+ cell infiltration into the tumor and is associated with signaling induction of p-STAT1." (PMID 34282238, 2021). "A major signaling hallmark of responders across cell categories was increased Stat1 expression, indicating a tumor-wide IFNγ response." (PMID 34433873, 2021). "To determine if STAT1 deficiency alters other subsets of myeloid cells, we examined the accumulation of neutrophils via Ly6G expression in the intestine during tumor development." (PMID 34299314, 2021). "Previous studies of Tet2-deficient tumor cells identified impaired STAT1 signaling that prevented the expression of chemokines and PD-L1 expression and enabled tumors to evade anti-PD-L1 immune therapy." (PMID 34417463, 2021). "The tumor suppression function of STAT1 has been associated with cell growth arrest, apoptosis, and inhibition of angiogenesis, but our studies suggest that STAT1 plays an important role in immune response modulation during inflammation-associated cancer." (PMID 34299314, 2021). "Anti-IL-17 treatment throughout the initial stages of CAC related to STAT1 deficiency abrogates the tumor formation possibly caused by myeloid cells." (PMID 34299314, 2021). "In the context of cancer, STAT1 is considered a tumor suppressor while STAT3 is often associated with tumor progression." (PMID 33526787, 2021). "We determined that an IL-17 blockade prevents tumor advance almost completely during STAT1 deficiency." (PMID 34299314, 2021). "Previously, we demonstrated the role of STAT1 as a tumor suppressor molecule in inflammation-associated carcinogenesis." (PMID 34299314, 2021).
tumor (continued). "In this study, we established that STAT1 deficiency deregulates the recruitment of myeloid cells via IL-17 during the early stages of tumor development." (PMID 34299314, 2021). "Prolonged IFN signaling enhanced STAT1-associated open chromatin, and leads to the expression of interferon-stimulated genes in tumor cells and induction of multiple T cell inhibitory receptor ligands." (PMID 34571790, 2021). "In high-grade serous ovarian carcinomas, elevated PD-L1 levels, indicative of increased STAT1 activation, is associated with elevated numbers of tumor-infiltrating lymphocytes and good outcome." (PMID 33807608, 2021). "This was reliant on PTPN2 deficiency driving the IFNγ‐induced and STAT‐1‐mediated expression of antigen‐presentation pathway genes and T‐cell chemoattractants, such as Cxcl9 in tumour cells." (PMID 31803974, 2020). "Up regulation of IFN mediated by STAT1 signal can be used in immunomodulating to avoid the risk of tumor occurrence, such as immune escape." (PMID 32294625, 2020). "STAT1-deficient mice are more prone to tumor development than animals with wild-type, indicating the central role of STAT1 in HCC progression." (PMID 32411519, 2020). "Evidence from STAT1 knockout mice models suggests that loss of STAT1 signaling results in enhanced tumor growth and increased number of exhausted T effector cells and TAMs." (PMID 33034643, 2020). "Genetic ablation of Stat1 in mice results in impaired NK cell maturation, cytotoxicity and NK cell-mediated tumor rejection, although underlying mechanisms are incompletely understood." (PMID 33042133, 2020). "In HCC, the expression of STAT1 has been reported to be lower in tumor tissues and is negatively associated with the histological grade." (PMID 30456450, 2019). "Together these data show that OGD conditions affect the IFNy responsiveness of tumor cells, which is associated with strongly decreased STAT1 activation." (PMID 31196219, 2019). "Where increased STAT3 activation is associated with tumor progression, it is often the loss of STAT1 and the associated pathway components that have been most widely explored in the context of cancer and immunity." (PMID 31842362, 2019). "IL-27p28, the ligand for IL27RA, has been linked with tumor progression, self-renewal and tumorigenicity, expression of inflammatory mediators, tumor immune invasion and regulated chemokine axis via STAT1/STAT3 signaling." (PMID 31628349, 2019). "This suggests that tumor cell‐intrinsic STAT1 is implicated in the invasion–metastasis cascade of male CRC patients at a stage beyond vein invasion." (PMID 29419930, 2018). "IHC stainings confirmed loss of STAT1 and pY‐STAT1 (activated STAT1) in tumor cells of male and female STAT1∆IEC mice, and no tumors that escaped STAT1 deletion were found." (PMID 29419930, 2018). "Early STAT1 deficiency promotes rapid and extensive intestinal damage, increased proliferation in the early stages of injury-induced tumor formation, and reduced apoptosis in advanced tumors." (PMID 30235866, 2018). "On the contrary, decreased STAT3 signaling caused an augment in STAT1 expression and reduced tumor growth." (PMID 30235866, 2018). "The transcription factor STAT3 is known to cause IL10-mediated suppression of both STAT1 as well as STAT1-mediated induction of the anti-tumor cytokine IL12." (PMID 30041669, 2018). "Signal transducer and activator of transcription 1 (STAT1) has been identified to be associated with tumor radioresistance." (PMID 29492196, 2018). "Of these proteins, STAT1 showed the greatest difference in expression between tumor subtypes and was associated with inflammation mediated by chemokine and cytokine signaling pathway." (PMID 29225558, 2017).
tumor (continued). "For example, the frequent KRAS mutation in CRC cells leads to inactivation of STAT1 and subsequent insensitivity of tumor cells to the anti-tumorigenic effects of IFN-γ." (PMID 26938566, 2016). "Loss of STAT1 is associated with a pronounced impairment of NK cell maturation, cytotoxicity and tumor surveillance." (PMID 27757297, 2016). "This confirmed our major conclusion, low STAT1/high STAT3 expression is associated with increased tumor growth." (PMID 27191495, 2016). "High ph-STAT1 tumour cell expression was associated with up-regulation of local inflammatory infiltrate as evidenced by increased generalised inflammatory cell infiltrate." (PMID 27769057, 2016). "Compared to wild-type, NK cells with mutated STAT1-S727A protein show enhanced cytotoxicity and tumor surveillance." (PMID 27757297, 2016). "High ph-STAT1 tumour cell expression was negatively associated with tumour necrosis (P=0.001), and was positively associated with the generalised inflammatory infiltrate as measured using Klintrup–Mäkinen (K-M) grade (P=0.007)." (PMID 27769057, 2016). "High ph-STAT1 tumour cell expression was positively associated with ER status (P=0.001), PR status (P=0.048), and negatively with increased tumour grade (P=0.015)." (PMID 27769057, 2016). "In line with the changes in STAT1 levels, STAT3 knockdown in HCT116 and SW620 (low STAT1+low STAT3) caused a faster xenograft tumor growth." (PMID 27191495, 2016). "High ph-STAT1 was significantly associated with improved CSS in luminal A (n=174) tumours (P=0.007)." (PMID 27769057, 2016). "High ph-STAT1 tumour cell expression was associated with improved CSS compared to low tumour cell expression (P=0.002)." (PMID 27769057, 2016). "Stat1 has been identified as a hub gene in several tumor-associated transcriptional networks including a gene network within HeLa cells exposed to IFNγ." (PMID 25902940, 2015). "The study revealed a link of potential mechanistic significance between elevated expression of STAT1 and its target genes with markers of infiltrating immune cells, in particular with tumor-associated macrophages." (PMID 24725474, 2014). "STAT1 was initially thought to be a tumor suppressor as STAT1-deficient mice developed tumors and STAT1-deficient cancer cells were found to be more resistant to chemotherapy." (PMID 25474038, 2014). "To clarify this issue we have determined STAT1 expression levels and activation by different methods, and investigated their association with tumor infiltration by immune cells." (PMID 24725474, 2014). "Tumors with increased STAT1 mRNA amounts exhibited elevated expression of genes characteristic for tumor-associated macrophages and immunosuppressive T lymphocytes." (PMID 24725474, 2014). "A higher density of CD33+/p-STAT1+ cells within tumor nests was associated with a lower density of CD8+ T cells (Spearman’s rho = −0.538, p < 0.001)." (PMID 23307253, 2013). "On the other hand, STAT1 overexpression is associated with tumor progression and acquisition of RT resistance." (PMID 23741352, 2013). "Our results support the body of evidence that STAT1 is associated with tumor suppressive properties, such as inhibition of angiogenesis, tumor growth and metastasis as well as promotion of apoptosis." (PMID 24274066, 2013). "We show that STAT1 deficiency significantly increases tumor incidence in BALB/c mice as well as decreasing disease latency." (PMID 22185785, 2011). "Stat1 primarily promotes growth arrest, apoptosis, and anti-tumour immunity downstream of type I and II interferons as demonstrated by the susceptibility of Stat1-deficient mice to develop tumours." (PMID 20478049, 2010).
tumor (continued). "Expression of invasion-associated markers and pathways (AKT, PI3 kinase, STAT1), identified in our in vitro models, will be further investigated in clinical tumor samples, with a focus on high grade, metastasizing and invasive cancers." (PMID 20454659, 2010). "Although the IFN-γ/STAT1 signaling is usually connected with anti-viral response and pro-apoptotic tumor-suppressor functions, constitutively activated IFN-γ/STAT1 pathway has been recently associated with aggressive tumor phenotypes." (PMID 21182795, 2010). "Recent observations from our laboratory indicate that resistance to STAT1 is also associated with resistance to the death ligands of the TNF receptor superfamily that are also involved in the control of tumor development." (PMID 19503789, 2009). "Emerging functions of a constitutively activated IFN/STAT1 pathway suggest an association with an aggressive tumor phenotype." (PMID 19503789, 2009). "Our results suggest that STAT1-associated transcriptional changes are also involved in regulation of the Warburg effect in tumour cells." (PMID 19891767, 2009). "STAT1 has been implicated in modulating pro- and anti-apoptotic genes following several stress-induced responses and therefore is able to act as a tumor suppressor." (PMID 16001973, 2005). "Additionally, continuous activation of the IFN-γ/STAT1 pathway and mutations in signaling molecules in tumor cells increase the likelihood of developing resistance to PD-L1 inhibitors." (PMID 40406250, 2025). "These outcomes, in conjunction with IFNγ-activated JAK/STAT1 signaling, promoted the trans-differentiation of tumor-associated macrophages from the M2 to M1 type, remodeled the suppressive tumor immune microenvironment created by iRFA, and restored therapeutic sensitivity to ICIs." (PMID 39776793, 2025). "Conversely, inhibition of STAT1 may skew neutrophils toward the N2 phenotype, which exhibits anti-inflammatory and tissue-repair properties, potentially attenuating tumor-associated inflammation and metastasis." (PMID 40226609, 2025). "Precancerous clusters showed enrichment in tumor progression-related regulons, including transcription factors (TFs) linked to tumor proliferation and cell cycle progression (STAT1, BCL6, ETV5) and potential tumor suppressors (ELF5, LTF, RXRG, CEBPD), as well as EMT-related regulons." (PMID 39872221, 2025). "While the phosphorylation of STAT1 is associated with the polarization of M1 macrophages that suppress cancer, it can paradoxically facilitate tumor growth by mediating immune suppression, highlighting its dual regulatory effect on tumor activity." (PMID 41362701, 2025). "Mechanistically, Ythdf1-deficient tumors exhibit enrichment of mature DCs (↑MHC-II, ↑IL-12), enhanced CD4+/CD8+ T-cell infiltration, and increased IFN-γ production, while activating the tumor cell IFN-γR1–JAK/STAT1 pathway, thereby heightening susceptibility to immune clearance." (PMID 41403953, 2025). "In addition, mfIHC results of pre‐therapy tumor tissues also indicated that the abundance of CD68+Stat1+ cells within pan‐CK+ tumor cells or CD8+ T cells was associated with a better response to immunochemotherapy in patients with ESCC." (PMID 40995650, 2025). "Although STAT1 is classically associated with tumor-suppressive interferon responses, mounting evidence suggests that in TNBC, STAT1 can acquire pro-tumorigenic functions, promoting stemness, proliferation, inflammatory cytokine production, and poor clinical outcomes." (PMID 41511309, 2025).